TTF1 (transcription termination factor 1)
Diseases named in the same sentence as TTF1 in open-access papers (continued):
Sharing a sentence is not in itself a finding about the gene and the disease.
Merkel cell carcinoma (9 papers, 2007 to 2025). "That two (7%) of our 28 Merkel cell carcinomas showed a moderate TTF-1 positivity is consistent with the sum of earlier data describing TTF-1 positivity in 0% of 12, 0% of 20, 8% of 52, 11% of 103, and 80% of 5 Merkel cell carcinomas." (PMID 39377914, 2024). "In one study, TTF-1 was reported to be positive in the vast majority of pulmonary (81%) and extra-pulmonary (80%) SmCC with the exception of Merkel cell tumor." (PMID 17803816, 2007). "Another study reported that TTF-1 was expressed in 82.7% of pulmonary SmCCs, 42.0% of extra-pulmonary SmCCs (range, 33.3 – 53.3% for the various sites), and 0% of Merkel cell carcinomas." (PMID 17803816, 2007). "However the presence of CK 20 +/TTF-1 – subset of CRSmCC highlights the morphological and immunohistochemical overlap between CRSmCC and Merkel cell carcinoma." (PMID 17803816, 2007). "However, some guidelines recommend thorough skin examination and immunohistochemical staining (IHC) for cytokeratin, TTF-1, CDX-2, and calcitonin for differential diagnoses, including paraganglioma, Merkel cell carcinoma, and MTC." (PMID 40747199, 2025). "For example, cytokeratin AE1/AE3, CK20, and PAX5 immunostains were ordered on aspirated material from parotid gland of a patient previously diagnosed for Merkel cell carcinoma to confirm a metastatic process or TTF‐1 and Napsin‐A were reviewed to rule out a metastatic lung adenocarcinoma." (PMID 35092649, 2022). "TTF-1 also helps to rule out Merkel cell carcinoma, where it is consistently negative." (PMID 27610258, 2016). "The importance of TTF-1 is to exclude metastatic Merkel cell carcinoma, which is TTF-1 negative." (PMID 18197972, 2008).
metastatic carcinoma (9 papers, 2008 to 2024). A carcinoma which has spread from the original site of growth to another anatomic site. "The tumor can simulate a metastatic carcinoma; however, the demonstration of thyroglobulin, TTF1, and PAX8 confirms the thyroid follicular origin." (PMID 32632840, 2020). "In any case, metastatic carcinoma cells from struma ovarii should disclosed positive immunoreactivity for TTF-1 and Tg." (PMID 25293503, 2014). "Then, the markers CKpan, CK7 and TTF1 were stained, and a metastatic carcinoma was confirmed." (PMID 37182167, 2023). "In contrast, a study by Prok demonstrated that in 16 of 43 patients with metastatic carcinoma of unknown primary to the brain, TTF-1 stained positive." (PMID 18817561, 2008). "If the differential diagnosis of a tumor sampled by needle core biopsy includes a metastatic carcinoma—such as a lung metastasis, then additional markers such as PAX8, TTF-1, and napsin A can be employed with the caveat that none of these markers are 100% specific or sensitive for a given diagnosis." (PMID 25889632, 2015).
renal cell carcinoma (9 papers, 2011 to 2025). "In contrast, thyroid transcription factor 1 (TTF-1), anti-renal cell carcinoma (RCC), CD10, CK20, as well as synaptophysin, chromogranin A, thyroglobulin and transthyretin are negative." (PMID 35546652, 2022). "Tumor cells were diffusely positive for CK7, EMA, and inhibin, while they were negative for CK20, P63, CK 5/6, CD10, renal cell carcinoma (RCC), TTF1, PAX8, CEA, and GATA3." (PMID 37261186, 2023).
lymphoma (8 papers, 2013 to 2025). A malignant (clonal) proliferation of B- lymphocytes or T- lymphocytes which involves the lymph nodes, bone marrow and/or extranodal sites. "The lead protein, tTF-NGR (Histag-tTF1-218-GNGRAHA), has recently entered a clinical phase I dose-escalation study in patients with advanced solid tumors or lymphomas beyond standard therapies (NCT02902237)." (PMID 32084238, 2020).
adenoma (7 papers, 2011 to 2022). A neoplasm arising from the epithelium. "Knocking out FILIP1L in mouse lungs led to TTF1-positive adenoma formation." (PMID 36860703, 2022). "However, targeting alveolar type II cells with Ad5-Sftpc-Cre in KF mice resulted exclusively in TTF1- and Sftpc-expressing adenomas and adenocarcinomas distributed in the alveolar area." (PMID 30642944, 2019). "Although TTF-1, Ki67, and PCNA are upregulated in the thyroid specimens of DMD-treated rats, especially in the regions with hyperplasia and adenoma formation, they are in relatively lower levels in the two resveratrol-treated groups." (PMID 29495605, 2018). "This was also confirmed in our study, where the adenoma was negative for TTF-1, whilst, as it was expected, the overlying epithelium clearly expressed TTF-1 antigen." (PMID 23533890, 2013).
gastric adenocarcinoma (7 papers, 2022 to 2026). "In gastric adenocarcinomas, we observed a positive immunohistochemical staining with antibodies against TTF-1 in 2 of 419 cases (0.5%)." (PMID 40564811, 2025). "Co-expression of TTF-1 and Napsin A was found in five cases, including three esophageal and two gastric adenocarcinomas." (PMID 40564811, 2025). "Only five tumors showed co-expression of TTF-1 and Napsin A, including three esophageal and two gastric adenocarcinomas." (PMID 40564811, 2025). "This analysis revealed an expression of at least one enteric marker in 22.1% of 68 TTF-1 positive pulmonary adenocarcinomas while TTF-1 positivity was also seen in 66 colorectal, 9 pancreatic, and 8 gastric adenocarcinomas." (PMID 39377914, 2024). "Positive TTF-1 staining could be detected in two cases (2/419; 0.5%) of gastric adenocarcinomas and positive Napsin A staining could be detected in in four cases (4/419; 1%) of gastric adenocarcinomas." (PMID 40564811, 2025). "We have previously reported that gastric adenocarcinoma of the fundic gland type shows high expression levels of SFTPB and SFTPC, both of which are transactivated by the ectopic expression of NKX2-1/TTF1." (PMID 37962678, 2024). "Combined analysis of TTF-1 and enteric markers revealed a positivity for TTF-1 and at least one enteric marker in 22% of pulmonary adenocarcinomas but also a TTF-1 positivity in 6% of colorectal, 2% of pancreatic, and 3% of gastric adenocarcinomas." (PMID 39377914, 2024). "However, TTF-1-positive primary gastric cancer could not be completely ruled out because there are reports describing TTF-1-positive gastric adenocarcinoma." (PMID 36459241, 2022).
cholangiocarcinoma (6 papers, 2014 to 2025). A carcinoma that arises from the intrahepatic biliary tree (intrahepatic cholangiocarcinoma) or from the junction, or adjacent to the junction, of the right and left hepatic ducts (hilar cholangiocarcinoma). "A biopsy of the liver mass revealed the presence of a poorly differentiated adenocarcinoma that was consistent with intrahepatic cholangiocarcinoma (CK7+, CEA+, CK20+, Hep-par 1−, TTF-1−)." (PMID 24550739, 2014). "The atypical glands were positive for CK7, while negative for CK20, CDX-2, and TTF-1, consistent with intrahepatic cholangiocarcinoma." (PMID 32724695, 2020).
colorectal adenocarcinoma (6 papers, 2017 to 2025). The most common type of colorectal carcinoma. "We report a rare case of TTF-1–positive metastatic colorectal adenocarcinoma to the lung in a 43-year-old man, illustrating a diagnostic pitfall." (PMID 41310725, 2025). "The goal of our study was to determine the frequency of TTF-1- and Napsin A-positive neoplasms in cohorts consisting of esophageal, gastric and colorectal adenocarcinomas." (PMID 40564811, 2025). "Thyroid transcription factor (TTF)-1 is expressed in the majority of pulmonary adenocarcinomas, but has only rarely been reported in adenocarcinomas originating at other sites, including colorectal adenocarcinoma." (PMID 28969003, 2017). "Histopathological examination revealed glandular structures resembling colorectal adenocarcinoma, with immunohistochemical positivity for CDX2, CK20, and SATB2, and negativity for TTF-1 and CK7." (PMID 41561768, 2025). "Using the clones SPT24 for TTF-1 and IP64 for Napsin A, we showed that these markers are expressed in a small number of esophageal, gastric and colorectal adenocarcinomas." (PMID 40564811, 2025). "The rectal cancer markers CK20 (+), CDX-2 (+), and SATB2 (+) are classic colorectal adenocarcinoma phenotypes, while CK7 (-), TTF-1 (-), and NapsinA (-) can exclude lung metastasis." (PMID 40837582, 2025). "In our case collections of gastrointestinal tumors, most cases with TTF-1 and/or Napsin A expression were CK20-positive and SATB2 expression was restricted to colorectal adenocarcinomas." (PMID 40564811, 2025). "The immunostaining profile of our patient (strongly positive CK7 and positive TTF-1 with negative CDX2/CK20) supported that her rectosigmoid tumor causing near-total rectal occlusion was metastatic adenocarcinoma of lung origin, rather than primary colorectal adenocarcinoma." (PMID 30961608, 2019). "This IHC staining profile (strongly positive CK7 and positive TTF-1/Napsin-A with negative CDX2/CK20) supported metastatic adenocarcinoma of lung origin, rather than primary colorectal adenocarcinoma." (PMID 30961608, 2019).
large cell neuroendocrine carcinoma (6 papers, 2011 to 2025). A usually aggressive carcinoma composed of large malignant cells which display neuroendocrine characteristics. "Brain tumor was resected with histology consistent with large cell neuroendocrine carcinoma with most likely lung primary because of TTF-1 positivity." (PMID 29147392, 2014). "Out of the 12 cryobiopsies conducted for lung malignancies, nine NSCLC (eight adenocarcinomas and one large cell neuroendocrine carcinoma) were valid for RT-PCR and PD-L1 IHC testing, leaving the EBUS-TBNA material for IHC determinations (p40 and TTF1)." (PMID 37998611, 2023). "The ACnP group comprised a higher proportion of non-adenocarcinoma histological subtypes, including large cell neuroendocrine carcinoma and pleomorphic carcinoma, and exhibited a greater frequency of tumors negative for thyroid transcription factor-1 (TTF-1)." (PMID 41300997, 2025). "TTF-1 and CD56 were negative in LCC and CK7 and 34bE12 were positive in large-cell neuroendocrine carcinomas." (PMID 36712764, 2022).
malignant mesothelioma (6 papers, 2013 to 2024). A malignant neoplasm of the pleura or peritoneum, arising from mesothelial cells. "TTF-1 immunohistochemistry (IHC) is therefore routinely used in surgical pathology to support the difficult distinction of primary pulmonary adenocarcinomas which are often TTF-1 positive from malignant mesothelioma and metastatic adenocarcinoma to the lung which are usually TTF-1 negative." (PMID 39377914, 2024).
ovarian carcinoma (6 papers, 2007 to 2025). A malignant neoplasm originating from the surface ovarian epithelium. "Indeed, the current case didn’t show typical clinical and gross features of metastasis, but histopathologic features and immunohistochemical results, notwithstanding occasionally reported TTF-1 expression in ovarian cancer, led us to make the correct diagnosis." (PMID 23663245, 2013). "Ovarian carcinoma binds antigens for CK7, CA125, ER, and is negative for CDX2, CK20, and TTF1." (PMID 18036260, 2007).
ovarian tumor (6 papers, 2013 to 2025). "The pathological findings of the ovarian tumor in this case, including the presence of thyroid follicle-like structures and positive immunohistochemical staining for Tg and TTF-1, supported a diagnosis of struma ovarii." (PMID 41322887, 2025). "Occasional expression of TTF-1 has been reported in ovarian neoplasms, and this should thus be taken into consideration when evaluating adenocarcinomas involving the lung in patients with CUP." (PMID 29433539, 2018). "In any case, pelvic imaging would be expected to reveal an ovarian tumour, and the tissue would have positive immunoreactivity to TTF-1 and Tg." (PMID 23533895, 2013).
prostate carcinoma (6 papers, 2012 to 2025). A carcinoma that arises from epithelial cells of the prostate gland. "The observed expression of PSA and absence of TTF-1 in Hoechst-stained nuclei are consistent with prostate cancer." (PMID 26695546, 2016). "Furthermore, some studies have observed that expression of CD155 could be induced by pathways such as Raf-MEK-ERK-AP-1 and through the Sonic Hedgehog pathway, which is highly active in advanced prostate cancer and can be indirectly mediated by STAT-3 via regulation of the TTF-1 promoter." (PMID 35465350, 2022). "Our prostate cancer patient demonstrated a CK7-positive, TTF-1-negative, PSA-positive profile in Hoechst-positive CTCs which can only be diagnosed as prostate cancer." (PMID 26695546, 2016). "In this case, the initial suspicion of prostate cancer was ruled out through comprehensive immunohistochemical (IHC) analysis, which revealed the absence of prostate-specific markers (PSA, NKX3.1) and the presence of lung-specific markers (TTF-1, Napsin A) in the prostate biopsy." (PMID 40740944, 2025).
renal carcinoma (6 papers, 2006 to 2025). A carcinoma arising from the epithelium of the renal parenchyma or the renal pelvis. "In addition, the absence of expression of TTF-1 and TG can be diagnostic of TLFCK, and TLFCK should be differentiated from other renal carcinomas." (PMID 24932236, 2014). "A positive staining for cytokeratin as well as for vimentin and CD10 in the absence of staining for thyroglobulin, calcitonin and TTF1, observed in smears from both lobes of the thyroid, favored the hypothesis of metastasis from a renal carcinoma." (PMID 17067398, 2006). "Furthermore, the IHC for CK20, CDx2, TTF1, CD10 and Vimentin showed a negative result, thus excluding metastases from gastrointestinal, lung, thyroid, renal cancer as well as sarcoma, respectively." (PMID 33912469, 2021).
brain tumors (5 papers, 2014 to 2025). "During routine diagnostics of brain tumours, we encountered an index case featuring “small blue round-cell” morphology, expression of TTF-1 and diffuse expression of synaptophysin." (PMID 39899075, 2025). "It seems important that TTF-1 protein expression can be examined when diagnosing primary brain tumors of uncertain nature." (PMID 39410026, 2024). "TTF-1 expression has been detected in brain tumors, including the pituitary gland and spindle cell oncocytoma." (PMID 39410026, 2024).
breast tumors (5 papers, 2010 to 2022). "The breast tumor was positive for thyroid transcription factor-1 (TTF-1), consistent with a lung primary cancer." (PMID 27488410, 2016). "This case describes an infiltrating breast tumour with thyroid transcription factor-1 (TTF-1) positive staining and ductal differentiation in a 72-year-old woman." (PMID 20565809, 2010).
colon adenocarcinoma (5 papers, 2007 to 2025). "CK-20 and CDX-2 are markers commonly associated with colonic adenocarcinoma, while TTF-1 and CK-7 are markers of pulmonary epithelial cells and pulmonary adenocarcinoma, respectively." (PMID 31484545, 2019). "Case reports of patients with TTF-1-positive colon adenocarcinoma are present in medical literature, but there are only a few cases of TTF-1-positive rectal adenocarcinoma." (PMID 30631609, 2018). "Eleven colon adenocarcinomas showed TTF-1 expression but no Napsin A positivity was recorded in these tumors." (PMID 40564811, 2025). "Colon adenocarcinoma stains positive for CK20 and typically negative for CK7, CA125, TTF1 and ER." (PMID 18036260, 2007).
gastric cancer (5 papers, 2017 to 2025). A primary or metastatic malignant neoplasm involving the stomach. "This concept is supported by the observation that a large proportion of TTF-1-positive colonic or gastric cancers also showed an immunohistochemical expression of at least one of the following markers: SATB2, CK20, FABP1, and Villin-1." (PMID 40564811, 2025). "If the 8G7G3/1 clone is applied, the proportion of TTF-1-positive gastric cancers appears to be somewhat higher." (PMID 40564811, 2025). "Immunohistochemical staining with Napsin-A and TTF-1 may help differentiating gastric metastases from primary gastric cancer." (PMID 35029172, 2022). "The gastric cancer markers CK7 (-), TTF-1 (-), and NapsinA (-) completely exclude lung derived metastasis, while Muc-2 (+), Muc-5AC (+), and Muc-6 (+) are gastric mucinous phenotypes, indicating gastric primordia." (PMID 40837582, 2025). "Thus, TTF-1-positive primary gastric cancer could not be completely ruled out." (PMID 36459241, 2022).
glioblastoma (5 papers, 2017 to 2025). The most malignant astrocytic tumor (WHO grade IV). "Although nuclear TTF1 expression in glioblastoma is rare, reactivity may differ among different antibody clones." (PMID 33876327, 2021). "We additionally stained 20 conventional glioblastomas, 10 of which were small cell variants, that were all negative for the TTF1 EP229 clone." (PMID 33876327, 2021). "TTF1 is known to be expressed during not only lung and thyroid morphogenesis but also during brain development which might lead to the assumption that positivity for this protein in glioblastomas might represent further evidence for a more primitive and undifferentiated phenotype." (PMID 33876327, 2021). "Regarding the TTF-1 positivity, staining remained positive in the recurrent tumor and TTF-1 positivity has been reported rarely in glioblastomas." (PMID 31806041, 2019). "We further compared the correlation between TTF1 and DLL3 protein in cell lines, and NKX2-1 and DLL3 mRNA in cell lines, an additional SCLC patient cohort and a cohort of glioblastoma patient samples and found significant correlations in each dataset." (PMID 29088717, 2017). "Our analysis of human cell lines, multiple patient cohorts (including both SCLC and glioblastoma), and mouse models revealed a strong, positive correlation between the expression of DLL3 and TTF1." (PMID 29088717, 2017). "It is well known that different TTF-1 clones show different reactivity in glioblastomas and non-neoplastic CNS tissue." (PMID 39899075, 2025). "We additionally stained glioblastomas with primitive neuronal component with the TTF1 8G7G3/1 clone shown to be negative in glioblastomas and only detected positive nuclear staining for TTF1 in one case." (PMID 33876327, 2021). "In addition, we detected positivity of tumor cell nuclei for TTF1 using the EP229 clone; whereas, conventional glioblastomas, including small cell variants, all stained negative for this clone." (PMID 33876327, 2021). "TTF1 expression in glioblastoma has not been described for this TTF1 clone so far." (PMID 33876327, 2021). "In contrast, all three glioblastoma SEGA-like cases were negative for TTF-1 expression." (PMID 31258848, 2019).
glioma (5 papers, 2011 to 2025). A benign or malignant brain and spinal cord tumor that arises from glial cells (astrocytes, oligodendrocytes, ependymal cells). "The expression of TTF-1 in pituitary cytomas and chordate gliomas prompted the hypothesis that these tumors may belong to a series of lineage-related tumors in the basal forebrain." (PMID 34210357, 2021). "To confirm the inhibitory effect of TTF-1 on the transcription of the COX-2 gene, we performed promoter assays using a luciferase construct containing the rat COX-2 promoter region (-2698 to +32) and a rat TTF-1 expression plasmid (TTF-1-pcDNA) in C6 glioma and B35 neuroblastoma cells." (PMID 22174936, 2011). "However, the immunohistochemical staining showed strong TTF-1 positivity, and it is possible that he had an occult lung primary tumor that was below the detection limits of the CT and MRI, or the tumor had originated from carcinogenesis in the tissues surrounding the former glioma site." (PMID 37771442, 2023). "It is also worth noting that nuclear TTF1 expression was only detectable in embryonal patterns in our tumors; whereas, glial tumor components did not express the protein." (PMID 33876327, 2021). "Furthermore, we propose testing for TTF-1 and neuronal marker expression in IDH-mutant gliomas showing primitive features to filter out patients that might benefit from extensive clinical monitoring." (PMID 39899075, 2025). "Overexpression of TTF-1 decreased mRNA and protein levels of COX-2 in the C6 glioma cells, but not in the B35 neuroblastoma cells." (PMID 22174936, 2011).